SLC4A4 (solute carrier family 4 member 4)
Diseases named in the same sentence as SLC4A4 in open-access papers (continued):
Sharing a sentence is not in itself a finding about the gene and the disease.
Stroke (5 papers, 2021 to 2025). Sudden impairment of blood flow to a part of the brain due to occlusion or rupture of an artery to the brain. "Of note, the blood vessel enlargement by loss of astrocytic Slc4a4 was much more pronounced after stroke compared to normal conditions (5-fold vs. 1.7-fold)." (PMID 38709635, 2024). "Using a mouse model of stroke, wefound loss of Slc4a4 exacerbates stroke-induced motor dysfunction, mortality and BBBdisruption coupled with impaired reactive gliosis." (PMID 34612709, 2021). "We next examined whether exacerbated extracellular acidity in Slc4a4-icKO mice is associated with more severe pathological presentations after stroke." (PMID 38709635, 2024). "Importantly, genetic deletion of the astrocyte-specific CCL2 restored vessel coverage by astrocytes and the number of vessel-associated astrocytes in Slc4a4-icKO mice after stroke." (PMID 38709635, 2024). "Collectively, our study defines a mechanism through which Slc4a4 affects BBB integrity by regulating reactive astrogliosis after stroke." (PMID 38709635, 2024). "The increased infarct volume in Slc4a4-icKO mice persisted until the stroke recovery stage at 14 dpi." (PMID 38709635, 2024). "We confirmed that Slc4a4 remains deleted in all the astrocytes in Slc4a4-icKO around the lesion area after stroke at 4 days post-injury (dpi)." (PMID 38709635, 2024). "Since inducible NOS (iNOS) is known to produce extra NO under injury, which is known to play a detrimental role in BBB function, we treated WT and Slc4a4-icKO mice with a selective iNOS inhibitor (1400W, 20 mg/kg) after stroke." (PMID 38709635, 2024). "Like pan-NOS inhibition, the iNOS inhibitor restores exacerbated BBB dysfunction and astrocytic CCL2 production in Slc4a4-icKO mice after stroke." (PMID 38709635, 2024). "Using this viral approach, we replicated key stroke-related phenotypes observed in the Slc4a4-icKO mouse line after the stroke, including enlarged infarct size, impaired reactive astrocytes response, increased transcellular and paracellular transport at the BBB, and increased capillary size." (PMID 38709635, 2024). "Moreover, we observed a partial but significant rescue of CCL2 overproduction in Slc4a4-icKO mice after stroke by an overall NOS inhibition." (PMID 38709635, 2024). "After stroke, deletion of astrocytic CCL2 rescued several phenotypes by Slc4a4 loss, including infarct size, BBB leakage, increased CD31 intensity, impaired tight-junctional marker expression (Claudin-5), and enhanced transcellular transport (pCav-1, Cav-1) surrounding the peri-lesion region." (PMID 38709635, 2024). "While our study found very low expression of CCR2 mRNA and protein in normal or stroked WT brain, consistent with previous endothelial transcriptome atlases, we found that loss of Slc4a4 results in an upregulation of endothelial CCR2, contributing to exacerbated BBB damage after stroke." (PMID 38709635, 2024). "We detected similarly low levels of Slc4a4 (encoding NBCe1) gene expression in MG3 compared to other microglia/macrophage subpopulations, but stroke triggered a small but significant increase of Slc4a4 gene expression in the MG3 of cKO brains (1.36-fold increase, p < 0.01)." (PMID 38509618, 2024). "Furthermore, Slc4a4-icKO mice exhibited a 3-fold increase in extracellular acidity range compared to WT at 1 dpi, suggesting that astrocytic Slc4a4 is required for maintaining pH homeostasis after stroke." (PMID 38709635, 2024). "Taken together, our results demonstrate that astrocytic Slc4a4 is required for re-establishing pH homeostasis and recovering BBB function after stroke." (PMID 38709635, 2024). "Further studies using either pharmacological or genetic inhibition of CCL2 and NO demonstrated the role of the Slc4a4 in regulating the CCL2-CCR2 pathway and NO metabolism in the context of BBB recovery after stroke." (PMID 38709635, 2024).
Stroke (continued). "Collectively, our data demonstrate the necessity of astrocytic Slc4a4 in maintaining BBB functions after stroke, which is independent of kidney Slc4a4 expression." (PMID 38709635, 2024). "Given the critical role of Slc4a4 in astrocytic interaction with endothelial cells and the key function of reactive astrocytes in BBB reconstruction after injury, we evaluated the role of Slc4a4 in reactive gliosis after stroke." (PMID 38709635, 2024). "To determine whether astrocytic Slc4a4 contributes to BBB remodeling after injury, we employed a cortical photothrombotic stroke (PTS) model." (PMID 38709635, 2024). "At the chronic stage of stroke (14 dpi), we did not observe any proliferating astrocytes at the peri-lesion area or the SVZ zone in either WT or Slc4a4-icKO mice." (PMID 38709635, 2024).
Acidosis (4 papers, 2014 to 2022). Abnormal acid accumulation or depletion of base. "For example, SLC4A4 has been demonstrated to be expressed in the colon and kidneys and knock out mice (NBCe1-/-) show metabolic acidosis and intestinal blockage (and references therein)." (PMID 24676142, 2014).
hemiplegic migraine (4 papers, 2011 to 2020). "SLC1A3 (encoding the glial glutamate transporter EAAT1) and SLC4A4 (encoding the electrogenic sodium bicarbonate cotransporter NBCe1) have been proposed as potential fourth and fifth genes (FHM4 and FHM5) responsible for pure hemiplegic migraine." (PMID 24403849, 2013). "More recently, a mutation in SLC4A4 encoding the Na+-HCO3- cotransporter NBCe1 has been identified in sisters with FHM, and a mutation in SLC1A3 encoding the glial glutamate transporter EAAT1 has been identified in one patient with pure hemiplegic migraine." (PMID 22027350, 2011).
Intellectual disability (4 papers, 2017 to 2021). "We report three consanguineous families in which an isolated ocular phenotype is linked to a novel 3′ UTR mutation in SLC4A4, a gene known to be mutated in a syndromic form of intellectual disability with renal and ocular involvement." (PMID 28754144, 2017).
pancreatic cancer (4 papers, 2021 to 2023). "Mazzone and colleagues identify the bicarbonate transporter SLC4A4 as highly abundant in epithelial duct cells in pancreatic cancer and show that its inhibition mitigates acidosis in the tumor, thereby alleviating immune suppression and overcoming immunotherapy resistance." (PMID 36522548, 2022). "In addition to its involvement in pancreatic cancer angiogenesis, the sodium bicarbonate transporter SLC4A4 is also related to invasiveness." (PMID 33783998, 2021). "Nevertheless, to date, there are no in vivo studies that have examined SLC4A4 as a modulator of tumor pH and antitumor immune responses in pancreatic cancer." (PMID 36522548, 2022). "Moreover, recent studies indicated that hsa‐miR‐223‐3p as an onco‐miRNA could suppress SLC4A4/KRAS signaling pathways and lead to cancer malignancy in kidney and pancreatic cancers." (PMID 36468451, 2023). "First, we generated mouse Panc02 and KPC pancreatic cancer cells engineered with a doxycycline-inducible CRISPR–Cas9 system and either a single guide RNA (sgRNA) targeting Slc4a4 (sgSlc4a4) or a non-targeting guide RNA (gRNA; sgNT) as a control." (PMID 36522548, 2022).
colon adenocarcinoma (3 papers, 2015 to 2023). "As a bicarbonate transporting proteins responsible for maintain PH equilibrium in the cells, SLC4A4 was downregulated in the colon adenocarcinoma and suppressed tumor development and metastasis." (PMID 35655081, 2022). "SLC4A4 is the top gene in our combined signature, with the highest absolute overall score, but the sign of the score is negative, which is in agreement with data from the Cancer Genome Atlas (TCGA) showing that SLC4A4 mRNA level is decreased in colon adenocarcinomas." (PMID 26356760, 2015).
ischemic stroke (3 papers, 2024 to 2025). A stroke disorder caused by obstruction of blood flow to the brain, due to thrombotic (local blood clot formation) or embolic (due to a blood clot or other material traveling from another site) event. "Using a model of ischemic stroke, we found that loss of Slc4a4 exacerbates BBB disruption, which was rescued by pharmacological or genetic inhibition of the CCL2-CCR2 pathway in vivo." (PMID 38709635, 2024). "Our results identified Slc4a4’s key role in astrocytogenesis during development and reactive gliosis following ischemic stroke injury." (PMID 38709635, 2024). "We first found that Slc4a4 was highly expressed in S100b+ reactive astrocytes, suggesting its potential role after ischemic stroke." (PMID 38709635, 2024). "We further measured cortical CCL2 levels, which were upregulated more than 2-fold in Slc4a4-icKO mice under normal and ischemic stroke conditions compared to WT." (PMID 38709635, 2024). "Together, these results provide an additional mechanism by which loss of Slc4a4 modulates BBB function and astrocytic CCL2 via regulating arginine to citrulline/NO conversion in the context of ischemic stroke." (PMID 38709635, 2024). "Together, these data indicate that loss of Slc4a4 impairs both local and SVZ astrocyte proliferation after cortical ischemia, which further leads to dampened reactive astrocyte response surrounding the lesion in both acute and chronic stages of ischemic stroke." (PMID 38709635, 2024). "This highlights Slc4a4’s role in regulating astrocyte-endothelial cell interaction, offering a critical regulatory mechanism for BBB recovery after ischemic stroke." (PMID 38709635, 2024). "Together, our study elucidates an indispensable role of Slc4a4 in astrocyte-BBB interaction, highlighting glial ion regulators as therapeutic targets for BBB-related pathology in ischemic stroke." (PMID 38709635, 2024). "ELISA showed that CCL2 was enriched in conditioned media from Slc4a4-depleted astrocytes under both normal (50% increase) and oxygen-glucose deprivation (OGD) conditions (70% increase), the latter mimicking in vivo ischemic stroke." (PMID 38709635, 2024). "In addition, loss of astrocytic Slc4a4 resulted in abnormal BBB structure and function in both normal and ischemic stroke brains." (PMID 38709635, 2024).
mastitis (3 papers, 2015 to 2024). Inflammation of breast tissue during lactation or postpartum due to an obstructed duct or infection. "A sequence-based association study of clinical mastitis to refine previously detected QTL regions suggested NPFFR2, SLC4A4, DCK, LIFR, and EDN3 as candidate genes for mastitis susceptibility." (PMID 27014337, 2016). "The comparison between these candidate QTL regions and known genes suggested that NPFFR2, SLC4A4, DCK, LIFR, and EDN3 may be considered as candidate genes for mastitis susceptibility." (PMID 26087655, 2015). "Furthermore, the comparison between these candidate QTL regions and known genes suggests that NPFFR2, SLC4A4, DCK, LIFR, and EDN3 may be considered as candidate genes for mastitis susceptibility." (PMID 26087655, 2015). "Therefore, NPFFR2, SLC4A4, DCK, LIFR, and EDN3 are candidate genes for susceptibility to mastitis." (PMID 26087655, 2015).
pancreatic ductal adenocarcinoma (3 papers, 2022 to 2025). An infiltrating adenocarcinoma that arises from the epithelial cells of the pancreas. "targeted a pre‐existing mechanism of pH regulation via the bicarbonate transporter SLC4A4 in pancreatic ductal adenocarcinoma." (PMID 36807529, 2023). "By single-cell RNA-sequencing analysis in individuals with pancreatic ductal adenocarcinoma (PDAC), we reveal solute carrier family 4 member 4 (SLC4A4) as the most abundant bicarbonate transporter, predominantly expressed by epithelial ductal cells." (PMID 36522548, 2022).
autism spectrum disorder (2 papers, 2021 to 2024). A spectrum of developmental disorders that includes autism, and Asperger syndrome. "Autism Spectrum Disorder, schizophrenia and major depression exhibited an overlap of two DEGs as well: SLC4A4 (Solute carrier family 4 member 4) and Y_RNA (RNA Gene Y RNA)." (PMID 39727940, 2024).
chronic myeloid leukemia (2 papers, 2016 to 2022). "Moreover, SLC4A4 expression was shown to be higher in chronic myeloid leukemia and mucinous epithelial ovarian cancer than in adjacent normal tissue, suggesting that the biological processes in which SLC4A4 is involved are tumor-specific." (PMID 35305629, 2022).
colorectal adenocarcinoma (2 papers, 2020 to 2023). The most common type of colorectal carcinoma. "SLC4A4 (NBCe1) is expressed in tissues such as the duodenum, jejunum and colon and in colorectal adenocarcinoma cells." (PMID 32662230, 2020). "In the colorectal adenocarcinoma LS174 cell line, mRNA expression of the Na+/HCO3‐ cotransporter SLC4A4 was induced in an oxygen‐induced HIF1α‐dependent manner, indicating that the reversal of the Na+/HCO3‐ exchanger is not used for tumour cell pHi regulation." (PMID 32662230, 2020).
corneal dystrophies (2 papers, 2013 to 2023). "Missense variants in heterozygosis were found in both GRHL1 (p.(Val287Gly)) and SLC4A4 (p.(Gly50Ala)), causally related to corneal dystrophies." (PMID 37895187, 2023). "Therefore, the purpose of this study was to characterize the expression levels of the entire Slc4 family of genes relative to those of Slc4a4 and Slc4a11 in the mouse corneal endothelium to identify further SLC4 members that can serve as candidate genes for analysis in corneal dystrophies." (PMID 23734078, 2013). "Given the known involvement of SLC4A4 and SLC4A11 in corneal dystrophies, we speculate that the other two highly expressed genes in the uncultured corneal endothelium, SLC4A2 and SLC4A7, are worthy of being considered as potential candidate genes for corneal endothelial diseases." (PMID 23734078, 2013).
depression (2 papers, 2022 to 2024). "SLC4A4 and Y RNA were significantly dysregulated in the ASD, schizophrenia and major depression datasets." (PMID 39727940, 2024). "Among the genes whose relevance in terms of belonging to a biological pathway is not at first obvious to relate to the pathophysiology of depression or the action of ADs is Slc4a4." (PMID 36362329, 2022).
glioblastoma (2 papers, 2018 to 2022). The most malignant astrocytic tumor (WHO grade IV). "Slc4a4, the gene that encodes NBCe1, is regulated by hypoxia in several epithelial cancer cell lines, but not in glioblastoma cell lines." (PMID 36012235, 2022).
Papillary Thyroid Carcinomas (2 papers, 2014 to 2021). "Two studies of papillary thyroid cancers (PTC) in patients of Polish and Korean descent showed that mRNA expression of SLC4A4 (NBCe1) was decreased by 7- and 3-fold, respectively, in PTC compared to normal tissue." (PMID 24795638, 2014).
renal carcinoma (2 papers, 2019 to 2021). A carcinoma arising from the epithelium of the renal parenchyma or the renal pelvis. "SLC4A4 overexpression restrained cell proliferation and metastasis by suppressing Kirsten rat sarcoma viral oncogene (KRAS) expression in renal cancer cells." (PMID 30668544, 2019). "Given that miR-223-3p suppressed the SLC4A4/KRAS axis, miR-223-3p gene therapy could be an effective treatment for renal cancer." (PMID 30668544, 2019).
schizophrenia (2 papers, 2022 to 2024). A major psychotic disorder characterized by abnormalities in the perception or expression of reality.
type 2 diabetes mellitus (2 papers, 2021 to 2023). A type of diabetes mellitus that is characterized by insulin resistance or desensitization and increased blood glucose levels. "Furthermore, SLC4A4 participates in the development of type 2 diabetes mellitus (T2DM), which is due to perturbation of the β cell’s transcriptional regulation." (PMID 37894847, 2023).
amelogenesis imperfecta (1 paper, 2021). Amelogenesis imperfecta (AI) represents a group of developmental conditions affecting the structure and clinical appearance of the enamel of all or nearly all the teeth in a more or less equal manner, and which may be associated with morphologic or biochemical changes elsewhere in the body. "Seven of the amelogenesis imperfecta-associated genes (CYP27B1, EPNN1, PHEX, SLC4A1, SLC4A4, VDR, and WDR72) are known to cause rickets when mutated." (PMID 33672174, 2021).
corneal diseases (1 paper, 2013). "When comparing the expression levels of the two clinically important genes known for corneal diseases (i.e., Slc4a11 and Slc4a4), the expression of Slc4a11 was approximately three times greater than that of Slc4a4 (3.4±0.3; p=0.004)." (PMID 23734078, 2013).
dengue (1 paper, 2015). "A recent study showed that analysis of seven genes (LOC286087, SLC4A4, PSPH, MYOM2, CACNA2D3, CD244 molecule, SMAD5) could possibly predict severe dengue since their expression profile was significantly lower in DHF patients compared to patients with DF." (PMID 26462910, 2015).
distal renal tubular acidosis (1 paper, 2024). A kidney disorder of impaired net acid secretion by the distal tubule characterized by hyperchloremic metabolic acidosis. "Here we report TOR measurements of the electrogenic Na+-CO32− cotransporter NBCe1-A (SLC4A4) and the kidney specific AE1 splice variant, kAE1, that play important roles in renal bicarbonate absorption and are mutated in proximal and distal renal tubular acidosis respectively." (PMID 39872416, 2024).
Fanconi syndrome (1 paper, 2025). "Ultimately, genetic testing revealed an SLC4A4 mutation, which is notably more often associated with proximal RTA and Fanconi syndrome but known in certain variants to produce overlapping or mixed tubular phenotypes." (PMID 41377247, 2025).
glioma (1 paper, 2011). A benign or malignant brain and spinal cord tumor that arises from glial cells (astrocytes, oligodendrocytes, ependymal cells). "Mutations in SLC4A4, another glial transporter that has been reported to cause FHM in two sisters, cause defective trafficking of NBCe1 and reduced intracellular alkalization in C6 glioma cells." (PMID 22027350, 2011).
ischemia reperfusion injury (1 paper, 2021). Adverse functional, metabolic, or structural changes in ischemic tissues resulting from the restoration of blood flow to the tissue (reperfusion), including swelling; hemorrhage; necrosis; and damage from free radicals. "Activation of SLC4A4 via inhibited the phosphorylated of P38 to limit the cell death in ischemia-reperfusion injury rat hearts 29; however, inhibition of JNK (SP600125, 10 uM) cannot effect SLC4A4 protein abundance in cortical astrocytes cells." (PMID 34405007, 2021).
metastasis (1 paper, 2021). The spread or migration of cancer cells from one part of the body (where they first appeared) to another. "Thus, it can be inferred that high level of SLC34A2 both closely interrelated capsular invasion risk and extra-thyroid metastasis risk, whereas low SLC4A4 level was only closely related to the risk of extra-thyroid metastasis." (PMID 34405007, 2021).
metastatic tumors (1 paper, 2023). "As shown in, SLC4A4 expression was significantly different in solid tissue normal (N = 41), primary (N = 286), recurrent tumors (N = 1), and metastatic tumors (N = 1)." (PMID 36468451, 2023).
osteoarthritis (1 paper, 2022). A noninflammatory degenerative joint disease occurring chiefly in older persons, characterized by degeneration of the articular cartilage, hypertrophy of bone at the margins and changes in the synovial membrane. "In this study, we found that overexpression of miR-16-5p inhibited expression of Eda, Relt, Slc4a4, and Smad3. miR-16-5p has been detected in osteosarcoma, osteoarthritis, and bone fracture healing." (PMID 35401675, 2022).